SNCB (synuclein beta)
Description:
Non-amyloid component of senile plaques found in Alzheimer disease. Could act as a regulator of SNCA aggregation process. Contributes to restore the SNCA anti-apoptotic function abolished by 6OHDA. Not found in the Lewy bodies associated with Parkinson disease.
Tractability: PROTAC: its protein half-life has been measured.
Gene: Protein-coding gene on chromosome 5 (176,620,082 to 176,630,672, reverse strand). Ensembl gene ENSG00000074317.
Subcellular location: Cytoplasm
Pathways (Reactome):
Cellular responses to stimuli: MTF1 activates gene expression
Gene Ontology:
Molecular function: calcium ion binding; cuprous ion binding; protein binding; transition metal ion binding; phospholipase inhibitor activity
Biological process: chemical synaptic transmission; synapse organization; synaptic vesicle endocytosis
Cellular component: inclusion body; axon terminus; cytoplasm; cytosol; neuronal cell body; synapse
Genetic constraint (gnomAD): Loss-of-function variants: 8 observed, 20.96 expected, observed/expected ratio (o/e) 0.38, 90% interval 0.22 to 0.69. The upper end of that interval is the gene's LOEUF score, 0.69, which puts it in group 2 of 6, group 1 being the genes least tolerant of losing a copy. Missense variants: 125 observed, 178.28 expected, observed/expected ratio (o/e) 0.7, 90% interval 0.61 to 0.81. Synonymous variants: 56 observed, 67.93 expected, observed/expected ratio (o/e) 0.82, 90% interval 0.66 to 1.03.
Homologues: Orthologues: chimpanzee SNCB (100% identical), guinea pig SNCB (98% identical), mouse Sncb (97% identical), rat Sncb (96% identical), dog SNCB (93% identical), pig SNCB (91% identical), tropical clawed frog sncb (86% identical), macaque SNCB (74% identical), zebrafish sncb (67% identical). Paralogues in human: SNCA (64% identical), SNCG (51% identical).
Diseases named in the same sentence as SNCB in open-access papers:
SNCB is named in the same sentence as 28 diseases in open-access papers, as found by Europe PMC text mining. Sharing a sentence is not in itself a finding about the gene and the disease. The quoted sentences say what the papers report.
glioma (3 papers, 2008 to 2022). A benign or malignant brain and spinal cord tumor that arises from glial cells (astrocytes, oligodendrocytes, ependymal cells). "Aberrant expression of AURKB, MPG and SNCB has been observed in cancers of neuronal cell types - gliomas, astrocytomas and medulloblastomas, respectively." (PMID 22087225, 2011). "Four genes have clearly identified functions in the central nervous system: APPA4 functions in Notch signaling during neural development, cell adhesion and apoptosis; RTN4 is a neurite growth inhibitor; and SNCB, which is upregulated in glial tumors, is thought to regulate phospholipase D2 activity." (PMID 18474104, 2008). "In total, we confirmed 14 genes with glioma-specific splicing; seven were novel events identified by the exon expression array (A2BP1, BCAS1, CACNA1G, CLTA, KCNC2, SNCB, and TPD52L2)." (PMID 18474104, 2008). "Among the 10 candidates, high mRNA expression of CCL8, FCGR2B, and TUBA4A and low mRNA expression of GABRD, PRAME, and SYN1 were significantly correlated with worse prognosis, while the mRNA expression of CCL18, SCN1B, SNCB, and VSNL1 showed no connection to the overall survival of glioma patients." (PMID 36685974, 2022).
Dementia with Lewy Bodies (2 papers, 2020 to 2024). "Even though only α-synuclein is thought to be involved in the pathophysiology of PD, patients with DLB (dementia with Lewy bodies) have been found to have lower levels of the SNCB transcript, and in vitro studies indicate that β-synuclein may antagonize α-synuclein-induced aggregation and toxicity." (PMID 38396996, 2024).
schizophrenia (1 paper, 2017). A major psychotic disorder characterized by abnormalities in the perception or expression of reality. "Additionally, Ingenuity Global Functional Analysis revealed significant enrichment of the identified protein dataset for proteins previously shown to be linked to schizophrenia, including GAP43, VDAC1 and SNCB, all of which have been shown to play a role in synaptic communication." (PMID 28570644, 2017).
neurodegenerative disease (2 papers, 2020 to 2022). A disorder of the central nervous system characterized by gradual and progressive loss of neural tissue and neurologic function. "Furthermore, downregulation of SNCB could occur not only in aggregation of SNCA, but also in other types of neurodegenerative disease." (PMID 32351728, 2020).
tumor (2 papers, 2014 to 2024). "A number of mitochondrial proteins with relevance to tumour pathophysiology were altered, including BSG, SNCB and three Isocitrate dehydrogenase 3 forms (IDH3A, IDH3B, and IDH3G)." (PMID 24728830, 2014). "Several proteins, for example BSG (increased in GBM), SNCB (decreased in GBM) and IDH3 (with IDH3A, IDH3G and IDH3B all decreased in GBM), did not fall into an obvious functional grouping but are pertinent to tumour pathophysiology (see “Discussion” section)." (PMID 24728830, 2014). "Neuron functional genes such as CaMK2N1, MEG3, SNCB, SYT1, DKK3 are almost expressed in the marginal area of the tumor (not shown)." (PMID 39257581, 2024).
SNCB also shares sentences with these, for which no sentence is quoted: Parkinson disease (7 papers); dementia (4); Alzheimer ́s disease (3); autism (2); prion disease (2); Synucleinopathies (2); amyloid (1); Anxiety (1); astrocytomas (1); autism spectrum disorder (1); Brain atrophy (1); cancer (1); cognitive decline (1); Cognitive impairment (1); Creutzfeldt Jacob disease (1); depression (1); ischemia (1); medulloblastoma (1); mood disorder (1); multiple sclerosis (1); neurological disorders (1); neurotoxicity (1); Parkinson’s (1).